IL33 (interleukin 33)
Diseases named in the same sentence as IL33 in open-access papers (continued):
Sharing a sentence is not in itself a finding about the gene and the disease.
osteoporosis (continued). "IL-33 has shown inhibitory properties in osteoporosis, a disease suggested to be promoted by IL-17." (PMID 32280308, 2020). "Better knowledge of the role of IL-31 and IL-33 and their receptor complexes in osteoporosis could provide an interesting perspective for the development of new and more effective therapies, possibly with less side effects." (PMID 32069819, 2020). "IL-33 acts at cellular, molecular, and transcriptional levels to mediate pluripotent functions in bone remodeling and has potential therapeutic value to mitigate osteoporosis." (PMID 32069819, 2020). "Furthermore, Th2 cells can contribute to osteoporosis via the IL-33/IL-31 axis." (PMID 41368642, 2025). "As there are no reports of IL-33 in aging bone-loss conditions, these background data deemed it reasonable to study the role of IL-33 in aging conditions as patients with dementia conditions like Alzheimer’s are at risk of osteoporosis." (PMID 39224568, 2024). "Furthermore, although serum IL-33 levels are lower in menopausal women with osteoporosis than those with normal BMD, the likely protective effect of IL-33 on the bone tends to disappear as the disease progresses, probably due to the interference of other osteoclastogenic cytokines." (PMID 32069819, 2020). "RAGE and its ligands HMGB and S100 alarmins, as well as IL-33, could also constitute potential biomarkers of bone disease progression and severity and could be useful in the diagnosis and follow-up of patients affected by osteoporosis." (PMID 32204562, 2020). "In the final stop of this tour de force of study, the authors demonstrated as a proof-of-principle of therapeutic potential that local delivery of IL-33 and CCL5 (separately) enhanced bone mass and function in the OVX rat model for osteoporosis." (PMID 41365059, 2025). "In postmenopausal women, osteoporosis serum levels of IFN-γ, IL-12p70, IL-33, IFN-α2, and MCP-1 were significantly elevated." (PMID 38817601, 2024). "The levels of cytokines (IFN-γ, IFNα2, IL-33, IL-12p70, IL-12p70) and MCP-1 in plasma were significantly higher in the osteoporosis group." (PMID 38817601, 2024). "Finally, the hypothesis that osteoblast HIF-1α pathway regulates osteoclastogenesis via IL-33-miR-34a-5p-Notch1 still needs to be confirmed in animal models of osteoporosis, and the clinical relevance of this pathway in osteoporosis or osteopetrosis remains to be elucidated." (PMID 29085370, 2017). "Contrary to IL-31, IL-33 inhibits bone resorption by inhibiting osteoclastic genes, including RANKL, which may become one of the key points to treat osteoporosis." (PMID 35707276, 2022). "The role of IL-33/ST2 axis in Th2/IL-31 and Th17 immune response characterizing the development of allergic respiratory pathologies has been clarified while the relationship between the two cytokines in osteoporosis is still controversial." (PMID 31973226, 2020). "Overall, our findings showed that in a group of apparently healthy postmenopausal women, cytokine levels of IFNα2, IFN-γ, IL-12p70, IL-33 and MCP-1 were significantly higher in groups with low bone mass (osteoporosis) than those with higher bone mass (osteopenia and healthy)." (PMID 31333751, 2019). "Not surprisingly, IL-33, which potently enhances Th2 immune response, could exhibit a prevalent protective role in osteoporosis, which is considered a Th1/Th17 cell mediated inflammatory disease." (PMID 30846811, 2019).
squamous cell carcinoma (19 papers, 2017 to 2025). A carcinoma arising from squamous epithelial cells. "Recently, studies have also revealed that the IL-33/ST2 axis is implicated in the immunopathogenesis of both esophageal adenocarcinoma and squamous cell carcinoma." (PMID 40520454, 2025). "Our group demonstrated that the IL-33/ST2 pathway enhances the development of squamous cell carcinoma (SCC)." (PMID 38662248, 2024). "In a study on squamous cell carcinoma of the tongue, patient tumor tissues were analyzed by immunohistochemistry for levels of IL-33 and ST2." (PMID 30205617, 2018). "IL-33 was shown to play a crucial role in tumor immunosuppression in murine squamous cell carcinoma (SCC) that is mediated by nuclear focal adhesion kinase (FAK)." (PMID 30205617, 2018). "Expression of IL-33 in squamous cell carcinoma and its relationship with clinical pathological characteristics of NSCLC." (PMID 29499051, 2018). "Correspondingly, UV-induced squamous cell carcinomas that evade the immune system were found to express significantly higher levels of IL-33." (PMID 30205617, 2018). "For the 22 squamous cell carcinoma tissues we examined, only 5 (22.7%) samples exhibited high IL-33 expression, whereas 20 (90.9%) of the adjacent normal tissues had high levels of IL-33 expression." (PMID 29499051, 2018). "However, the crosstalk between IL-33, cancer and immune cells in squamous cell carcinoma (SCC) remains unclear." (PMID 38662248, 2024). "The expression levels of IL-33 and ST2 were found to be significantly downregulated in both adenocarcinoma and squamous cell carcinoma of the lung compared to adjacent normal lung tissues." (PMID 37719702, 2023). "Nuclear IL-33 mediates focal adhesion kinase (FAK)-dependent secretion of soluble ST2, a decoy receptor, and CCL5 from squamous cell carcinoma cells, which stimulates immunosuppressive Tregs leading to cancer immune evasion." (PMID 35432341, 2022). "Furthermore, IL-33 induces the recruitment of a subset of tumor-associated macrophages, which express ST2 and high-affinity IgE receptor, FcεRIα, and produce TGF-β, in the tumor microenvironment, which results in tumor progression in a mouse model of squamous cell carcinoma." (PMID 35432341, 2022). "In this study, we showed that IL-33 as well as its receptor ST2 were significantly down-regulated in both adenocarcinoma and squamous cell carcinoma of the lung when compared to adjacent normal lung tissues." (PMID 29499051, 2018). "The expression levels of IL-33 and ST2 were significantly down-regulated in both adenocarcinoma and squamous cell carcinoma of the lung when compared to adjacent normal lung tissues." (PMID 29499051, 2018). "IL-33 is upregulated in squamous cell carcinoma (SCC), and mast cell activation by IL-33 occurs in skin cancers." (PMID 28446910, 2017). "IL-33 expression in squamous cell carcinomas inversely correlated with tumor size rather than tumor grade (P = 0.043)." (PMID 29499051, 2018). "Increases in the expression of IL-33/ST2 axis components have been demonstrated to contribute to neoplastic transformation in several tumor models and interleukin-33 is correlated with poor prognosis of patients with squamous cell carcinoma of the tongue." (PMID 30112116, 2018). "We have shown that IL-33 was down-regulated in tumor tissues compared to adjacent normal tissues and its expression in tumor was inversely correlated with tumor grade in adenocarcinoma and with tumor size in squamous cell carcinoma of NSCLC." (PMID 29499051, 2018).
experimental autoimmune encephalomyelitis (18 papers, 2015 to 2025). An autoimmune demyelinating disease of the central nervous system that is produced experimentally in animals by the injection of homogenized brain or spinal cord in Freund's adjuvant. "IL-33 knockout of activated astrocytes and microglia in the experimental autoimmune encephalomyelitis mice showed a protective effect of IL-33, with increased production of TNF-α in primary microglia and astrocytes." (PMID 39925809, 2025). "In experimental autoimmune encephalomyelitis, IL-33 treatment reduces the concentrations of IL-17 and IFN-γ, alleviating disease progression." (PMID 40764944, 2025). "IL-33 is known to attenuate IL-17 expression in EAE Experimental autoimmune encephalomyelitis and so D-gal–exposed osteoblasts were treated with IL-17 alone and with IL-33." (PMID 39224568, 2024). "Studies also indicate that there is a relationship between IL-33 and the Th17 response, one study reported that IL-33 was able to suppress IL-17A production by attenuating experimental autoimmune encephalomyelitis." (PMID 34324507, 2021). "The amelioration of the clinical symptoms of experimental autoimmune encephalomyelitis along with decreased IL-33 expression with vitamin D suggests the immunomodulatory and anti-inflammatory effects of vitamin D." (PMID 34842603, 2021). "In experimental autoimmune encephalomyelitis, males produce higher IL-33 levels, promoting a non-pathogenic Th2 response, whereas females, with a lower IL-33 response, develop a more pathogenic Th17-dominant response." (PMID 40551129, 2025). "Recent studies showed that astrocyte-secreted cytokines, such as IL3 and IL33, control microglia recruitment and activation, leading to astrocyte pathogenic activation and neuronal injury in AD and EAE (experimental autoimmune encephalomyelitis) subsequentially." (PMID 39886603, 2025). "In addition, ginger extract rich in gingerol and shogaol has been reported to have shown the effect of improving clinical symptoms of the disease with the regulation of IL-33 expression in experimental autoimmune encephalomyelitis mouse models." (PMID 39765899, 2024). "Additionally, inhibition of IL-33 with neutralizing antibodies resulted in reduced pathology in experimental autoimmune encephalomyelitis and MRL/lpr mouse models." (PMID 30574145, 2018). "Additionally, it has been shown in experimental autoimmune encephalomyelitis that IL-33 is capable of diminishing the secretion of inflammatory cytokines such as IFN-γ (Th1) and IL-17 (Th17)." (PMID 26677348, 2015). "Targeting IL-33 to improve disease outcome has been promising in other neurodegenerative diseases such as experimental autoimmune encephalomyelitis (EAE) and Alzheimer’s; therefore, investigating the IL-33:ST2 axis in skeletal muscle pathology and glial toxicity in ALS might be beneficial." (PMID 29473876, 2018). "IL-33, a member of the IL-1 superfamily of cytokines, has been shown to decrease IL-17 and IFN-γ production in an experimental autoimmune encephalomyelitis (EAE) model." (PMID 34012433, 2021). "Some studies have also shown that IL-33 can induce the production of IFN-γ in animal models of experimental autoimmune encephalomyelitis (EAE), suggesting that IL-33 can induce type 1 as well as type 2 depending on the type of stimuli." (PMID 35118069, 2021). "For example, in the experimental autoimmune encephalomyelitis (EAE) model, some investigators have reported that IL-33 blockade during the developing stage of MOG-induced EAE reduces the severity of the disease, in part, due to the inhibition of MOG-dependent IL-17 and IFN-γ production." (PMID 26082774, 2015).
gastritis (18 papers, 2015 to 2026). Inflammation of the stomach. "Recently, gastric IL-33 was found to be increased in the gastric epithelium of patients and mice with Hp infection, a result associated with the degree of bacterial expansion and the severity of gastritis." (PMID 39728753, 2024). "Therefore, IL-33 is critical in H. pylori-associated gastritis and GC." (PMID 36275647, 2022). "Research shows that IL33 can promote metaplasia formation in gastritis-prone mice by triggering eosinophil-dependent events, providing important mechanistic insights into how inflammatory microenvironment influences SPEM origins." (PMID 41479779, 2025). "This study showed that H. pylori infection induced gastritis by increasing gastric inflammation, IL-17, IL-33, and EGF production and decreasing PGE2 levels." (PMID 39857676, 2025). "IL-33 is released after parietal cell death; reduction of IL-33 reduced gastritis and downstream gastric metaplasia in mice." (PMID 39193325, 2024). "Locally, H. pylori-related IL33 appears to orchestrate MC responses and promote bacterial expansion, thus implicating the induction of gastritis." (PMID 38673633, 2024). "The study provided evidence of Hp, gastric epithelial cells, IL-33, MCs, and TNF-α forming a complex regulatory network that, when disrupted, contributes to Hp infection-associated gastritis." (PMID 39728753, 2024). "Herein, we confirm that IL-33 is highly expressed in gastric mucosa during gastritis, and we have identified contrasting effects of this molecule on normal and neoplastic gastric epithelium." (PMID 34071419, 2021). "IL33 expression can be detected in normal gastric mucosa, and it becomes higher in patients with asymptomatic gastritis." (PMID 33426088, 2020). "H. pylori infection upregulated mucosal IL-33 mRNA expression in patients with gastritis, indicating that IL-33 exacerbates the inflammatory response in the gastric mucosa." (PMID 31640262, 2019). "To understand if the effects of H. pylori-induced IL-33 expression can be replicated in vivo and induce stomach inflammation, we infected mice with H. pylori (1 × 108) by intragastric gavage once every 2 days for a total of six administrations." (PMID 31640262, 2019). "In turn, TNF-α aggravates the inflammation and H. pylori colonization; furthermore, IL-33 inhibits gastric epithelial cell renewal and promotes gastritis progress." (PMID 29691371, 2018). "But our results showed that IL-33 had a maximal expression in the mice gastritis model infected by H. pylori (11637 strain) at approximately the 2-month point p.i." (PMID 29691371, 2018). "In consideration of the notable relationship between the expression level of IL-33 and the severity of gastric inflammation observed in H. pylori-infected patients, it is possible that IL-33 might serve as a novel diagnostic and prognostic biomarker for H. pylori-associated gastritis." (PMID 29691371, 2018). "And then, IL-33 enhances mast cell-derived tumor necrosis factor-alpha (TNF-α) secretion in gastritis." (PMID 29691371, 2018). "In our animal model, H. pylori infection of Dmbt1−/− mice resulted in significantly higher levels of gastritis, more extensive mucous metaplasia and reduced Il33 expression levels in the gastric mucosa compared to H. pylori-infected wild type mice." (PMID 28423364, 2017). "This study evaluated IL-33 mucosal mRNA expression levels in infected and uninfected patients and its relationship with bacterial virulence factors cagA, babA2 and type of gastritis." (PMID 27014647, 2015). "Like our results, another study in 2015 showed that IL-33 mRNA expression was increased in active gastritis biopsies more than chronic gastritis samples." (PMID 27014647, 2015). "In the present study, IL-33 mRNA expression was significantly high in babA2 positive H. Pylori infected patients as well as active gastritis patients." (PMID 27014647, 2015).
gastritis (continued). "Gastric IL-33 resulted in increased TNF-α production from MCs in vitro, and in vivo and inhibited gastric epithelial cell proliferation, thus further promoting Hp-associated gastritis and bacteria proliferation." (PMID 39728753, 2024). "Furthermore, studies in a long-term adrenalectomy SPEM model have shown that SPEM progression is delayed in only IL-33 KO mice and that treatment of mice with recombinant IL-33 induces gastritis with a potential SPEM phenotype." (PMID 36275647, 2022). "Furthermore, IL-33 production is promoted by NOD1 signaling in chronic H. pylori-infected gastritis, which prevents excessive inflammation." (PMID 36275647, 2022). "In gastritis, the relationship between IL33 and adaptive immune cells needs further confirmation." (PMID 33426088, 2020). "Additionally, IL-33 mRNA expression levels were significantly lower in patients with chronic gastritis, as compared to those with active gastritis." (PMID 31320834, 2019). "Here, we found that gastric IL-33 mRNA and protein expression were elevated in gastric mucosa of both patients and mice infected with H. pylori, which is positively correlated with bacterial load and the degree of gastritis." (PMID 29691371, 2018). "IL-33 represents a recently discovered proinflammatory cytokine involved in inflammatory diseases, but its relevance to H. pylori-induced gastritis is unknown." (PMID 29691371, 2018). "Furthermore, IL-33 mRNA expression level was significantly lower in chronic gastritis patients compared with patients with active gastritis (P<0.001)." (PMID 27014647, 2015). "This study evaluated IL-33 mucosal mRNA expression levels in infected and uninfected patients and assessed its relationship with bacterial virulence factors cagA, babA2 and type of gastritis." (PMID 27014647, 2015). "If the mean of IL-33 mRNA level in chronic gastritis group is 0.0031 and the mean of IL-33 mRNA level in active gastritis group is 0.0083 then the difference in the IL-33 mRNA expression in the active gastritis compared with the chronic gastritis biopsies is 0.0083/0.0031 or 2.67 fold." (PMID 27014647, 2015). "Our data suggest that reduction in IL-33 mRNA expression level may be a biomarker for predicting the prognosis of gastritis, especially in chronic gastritis which is an initiation for gastric ulcer." (PMID 27014647, 2015). "In addition to IL33, MC chymase may be another significant contributor to H. pylori-induced gastritis." (PMID 38673633, 2024). "However, a chronic infection state is more prominent in patients with H. pylori-associated gastritis and the potential role, if any, of IL-33 has not been elucidated." (PMID 29691371, 2018). "Targeting cytokines, such as IL-33, was effective in modulating the downstream recruitment and activation of immune cells, such as eosinophils, M2 macrophages, and ILC2, reducing gastritis and downstream gastric metaplasia." (PMID 39193325, 2024). "IL-33 upregulation promotes the development of chronic atrophic gastritis, SPEM, GC.IL-33 upregulation promotes SPEM formation after acute gastric injury.IL-33 upregulation is associated with injury and repair in H. pylori-associated gastritis." (PMID 36275647, 2022). "Although IL-33 reportedly plays a pivotal role in gastritis exacerbation, a recent study revealed that NOD1 is required for H. pylori-induced IL-33 production and that this confers a protective role against inflammation." (PMID 31640262, 2019). "Chronic atrophic gastritis, spasmolytic polypeptide-expressing metaplasia (SPEM) and GC are states along the continuous developmental trajectory of gastric mucosal disease, and IL-33 is a potential promoter of this process." (PMID 36275647, 2022). "Moreover, IL-33 also induced TNF-α production by mast cells, which facilitated H. pylori colonization and worsened gastritis." (PMID 31640262, 2019). "Moreover, the upregulated IL-33 induced mast cells to secrete TNF-α, which inhibited gastric epithelial cell renewal and aggravated gastritis." (PMID 29691371, 2018).
gastritis (continued). "This led us to hypothesize that, during H. pylori infection, IL-33 might exert proinflammatory effects and promote TNF-α production and, as a result, lead to gastritis." (PMID 29691371, 2018). "Our findings provide insights into how IL-33, mast cells, TNF-α, and gastric epithelial cells may interact in H. pylori-induced gastritis." (PMID 29691371, 2018).